HMG20A (high mobility group 20A)
Description:
Plays a role in neuronal differentiation as chromatin-associated protein. Acts as inhibitor of HMG20B. Overcomes the repressive effects of the neuronal silencer REST and induces the activation of neuronal-specific genes. Involved in the recruitment of the histone methyltransferase KMT2A/MLL1 and consequent increased methylation of histone H3 lysine 4 (By similarity).
Synonyms: HMGX1; HMGXB1; FLJ10739
Tractability: PROTAC: ubiquitination databases record sites on it; its protein half-life has been measured.
Gene: Protein-coding gene on chromosome 15 (77,419,830 to 77,485,955, forward strand). Ensembl gene ENSG00000140382.
Subcellular location: Nucleus
Subcellular location (Human Protein Atlas): Nucleoplasm
Gene Ontology:
Molecular function: identical protein binding; protein binding
Biological process: chromatin organization; regulation of DNA-templated transcription; regulation of gene expression
Cellular component: nucleus
Genetic constraint (gnomAD): Loss-of-function variants: 12 observed, 33.42 expected, observed/expected ratio (o/e) 0.36, 90% interval 0.23 to 0.58. The upper end of that interval is the gene's LOEUF score, 0.58, which puts it in group 2 of 6, group 1 being the genes least tolerant of losing a copy. Missense variants: 270 observed, 360.89 expected, observed/expected ratio (o/e) 0.75, 90% interval 0.68 to 0.83. Synonymous variants: 106 observed, 122.98 expected, observed/expected ratio (o/e) 0.86, 90% interval 0.74 to 1.01.
Homologues: Orthologues: macaque HMG20A (100% identical), chimpanzee HMG20A (99% identical), pig HMG20A (98% identical), guinea pig HMG20A (97% identical), dog HMG20A (96% identical), mouse Hmg20a (96% identical), rat Hmg20a (96% identical), rabbit HMG20A (95% identical), zebrafish hmg20a (62% identical), tropical clawed frog hmg20a (56% identical), Caenorhabditis elegans hmg-3 (9% identical), Caenorhabditis elegans hmg-4 (9% identical). Paralogues in human: HMG20B (43% identical), SMARCE1 (19% identical), TOX4 (15% identical), TOX3 (14% identical), TOX (14% identical), TOX2 (13% identical), UBTF (13% identical), HMGXB4 (12% identical), SP140 (11% identical), HMGB1 (10% identical), HMGB3 (10% identical), HMGB2 (10% identical), and 8 more.
Diseases named in the same sentence as HMG20A in open-access papers:
HMG20A is named in the same sentence as 26 diseases in open-access papers, as found by Europe PMC text mining. Sharing a sentence is not in itself a finding about the gene and the disease. The quoted sentences say what the papers report.
type 2 diabetes (8 papers, 2012 to 2024). "We next attempted to understand further the associations between SNPs in the LAMA1 and HMG20A loci and lean and obese type 2 diabetes cases respectively." (PMID 22693455, 2012). "In the obese case analysis, the HMG20A signal was associated with type 2 diabetes (combined P = 1.3×10−8, OR = 1.11 [1.07–1.15], total obese cases N = 8,583, controls = 62,063) compared to an OR = 1.09 [1.02–1.17], P = 0.015, in the lean analysis." (PMID 22693455, 2012). "The rs7178572 SNP in the HMG20A region was significantly associated with mRNA expression levels of HMG20A in the liver (P = 4×10−5), supported by two separate expression probes, and was the strongest known regional SNP for both the liver eQTL and type 2 diabetes." (PMID 22693455, 2012). "The enrichment of the LAMA1 signal in lean type 2 diabetes cases compared to obese cases is likely to be a real effect but the enrichment of the HMG20A signal in obese cases is more likely to be due to chance." (PMID 22693455, 2012). "In conclusion, we report associations with the LAMA1 and HMG20A (not previously associated at genome-wide significance in Europeans) gene regions with type 2 diabetes risk." (PMID 22693455, 2012). "One SNP, rs7178572 in HMG20A, had a nominal association with type 2 diabetes (p<0.05); however, this association was not significant after Bonferroni’s correction." (PMID 23029454, 2012). "Notably, a CDKAL1 variant (rs7766070) confers the highest level of risk while rs7119 (HMG20A) and rs708272 (CETP) have high risk allele frequencies in this population at 0.77 and 0.66, respectively, making them potentially good markers for type 2 diabetes mellitus screening." (PMID 39561140, 2024). "A variant in HMG20A—previously identified in South Asians but not Europeans—was associated with type 2 diabetes in obese cases (P = 1.3×10−8, OR = 1.11 [95% CI 1.07–1.15]), although this association was not significantly stronger than that in lean cases (P = 0.02, OR = 1.09 [95% CI 1.02–1.17])." (PMID 22693455, 2012). "Regarding the remaining 6 loci derived from a South Asian GWAS, rs7178572 in the intron of HMG20A was nominally associated with type 2 diabetes; however, no SNPs showed a significant association with type 2 diabetes in the present Japanese population after correction for multiple testing errors." (PMID 23029454, 2012). "Recently small nucleotide polymorphisms (SNPs) in the HMG20A gene have been linked to type 2 diabetes mellitus (T2DM) yet neither expression nor function of this T2DM candidate gene in islets is known." (PMID 29449530, 2018). "In another study, allele-specific expression of several genes in islets (ANPEP, CAMK2B, HMG20A, KCNJ11, NOTCH2, SLC30A8 and WFS1) showed that even subtle changes of gene dosage may have significant consequences for development of type 2 diabetes." (PMID 30497374, 2018). "By stratifying type 2 diabetes into two well accepted definitions of lean and obese cases, we identified and replicated one locus in each BMI stratum, each previously unreported in European studies: a signal in the LAMA1 gene in the lean stratum and a signal in the HMG20A gene in the obese stratum." (PMID 22693455, 2012).
diabetes (6 papers, 2018 to 2024). "A significant finding of our study is the potential decreased in HMG20A levels associated with the diabetes-linked rs7119 SNP within the 3′ UTR of the transcript." (PMID 29449530, 2018). "The overall aim of the current study was to assign a functional role of the putative diabetes-linked HMG20A gene to islet physiology, and determine the pathophysiological consequence of the rs7119 SNP associated with this disease." (PMID 29449530, 2018). "Rationale: We recently demonstrated that the 'Metabesity' factor HMG20A regulates islet beta-cell functional maturity and adaptation to physiological stress such as pregnancy and pre-diabetes." (PMID 34093866, 2021). "We propose that such a sensor can be the chromatin-remodeling protein HMG20A, thus becoming an interesting target for reverting metabesity and diabetes." (PMID 31072002, 2019). "Interestingly, although HMG20A was repressed by palmitate in vitro, expression levels were not significantly altered in islets of a mouse model of high fat diet-induced obesity and pre-diabetes." (PMID 29449530, 2018).
Obesity (4 papers, 2018 to 2022). Accumulation of substantial excess body fat. "The treatment with ORY1001, a drug mimicking HMG20A, protected mice from the obesity-associated glucose intolerance." (PMID 36131679, 2022). "Furthermore, ORY1001 treatment protected against obesity-associated glucose intolerance in mice correlating with a regression of hypothalamic HMG20A expression, indicative of reactive astrogliosis attenuation with improved health status." (PMID 34093866, 2021). "HMG20A expression was upregulated in diet-induced obesity and glucose intolerant mice, correlating with increased transcript levels of Gfap and Il1b indicative of inflammation and reactive astrogliosis." (PMID 34093866, 2021). "Under physiological pressure such as obesity and insulin resistance that induces low grade inflammation, HMG20A expression is increased to induce reactive astrogliosis in an attempt to preserve the neuronal network and re-establish glucose homeostasis." (PMID 34093866, 2021). "Importantly for clinical relevance, transcription of HMG20A was observed in adipose tissue of diabetic patients with obesity." (PMID 36131679, 2022). "We also assessed whether HMG20A is expressed in human white adipose tissue (WAT) and serum and whether its levels correlate with obesity and/or T2DM." (PMID 34093866, 2021). "HMG20A regulates metabolism-secretion coupling genes in beta cells and could be also involved in beta cell plasticity through PAX4 and REST, regulating phenotypic changes needed for beta cells in order to respond to different physiological situations as pregnancy and obesity." (PMID 29449530, 2018).
Glucose intolerance (2 papers, 2018 to 2021). Glucose intolerance (GI) can be defined as dysglycemia that comprises both prediabetes and diabetes. "Pregnant females displayed mild glucose intolerance at 14.5 correlating with the peak in HMG20A protein levels." (PMID 29449530, 2018). "Finally, we evaluate the potential therapeutic benefits of ORY1001 (aka, Ladademstat), a potent inhibitor of the LSD1-CoREST complex that mimics the effects of HMG20A, to revert high fat diet-induced glucose intolerance and neuroinflammation." (PMID 34093866, 2021).
Hyperglycemia (2 papers, 2018 to 2021). An increased concentration of glucose in the blood. "As such, under environmental insults such as hyperglycemia, HMG20A could activate on one hand the adaptation pathways conveying maturation/functionality of beta cells in islets and on the other hand transitory reactive astrogliosis and neuronal protection in CNS." (PMID 34093866, 2021). "A similar regulatory cross talk between HMG20A and PAX4 may also be operative in early stages of hyperglycemia, which is characterized by active beta cell adaptation." (PMID 29449530, 2018).
abnormal glucose tolerance (1 paper, 2019). An abnormal resistance to glucose, i.e., a reduction in the ability to maintain glucose levels in the blood stream within normal limits following oral or intravenous administration of glucose. "Supporting this likely role of HMG20A in islet adaptation processes during pregnancy, polymorphisms/mutations in HMG20A have also been associated with GDM as well as with postpartum abnormal glucose tolerance." (PMID 31817798, 2019).
colon cancer (1 paper, 2022). "Consistent with in vitro experimental results, HMG20A in combination with SFMBT1 drive colon cancer tumorigenesis and 5-FU resistance in vivo." (PMID 35577773, 2022). "Given TCGA and GEPIA database information of SFMBT1 and HMG20A in cancer, we speculated that HMG20A might be involved in colon cancer tumorigenesis and drug resistance with SFMBT1." (PMID 35577773, 2022). "To investigate the function of HMG20A in combination with SFMBT1 in colon cancer in vivo, we studied xenograft tumors derived from HCT-116/5-FU cell transfected with SCR, sh-HMG20A, sh-HMG20A + scr and sh-HMG20A + sh-SFMBT1." (PMID 35577773, 2022).
Corneal astigmatism (1 paper, 2023). "By using a GWAS approach, SNPs near TJP2, PCBP3, CADM2, and TRPM3 were identified to be associated with myopia or refractive errors, and HMG20A and PPP2R2B were associated with axial length and corneal astigmatism, respectively." (PMID 37449273, 2023).
gestational diabetes (1 paper, 2021). Carbohydrate intolerance first diagnosed during pregnancy. "Consistent with these functional data small nucleotide polymorphisms (SNPs) in the HMG20A gene have been associated to T2DM as well as gestational diabetes mellitus (GDM) in Asian/Indian and European populations 19-25." (PMID 34093866, 2021).
lung carcinoma (1 paper, 2024). "CREB activation upregulates the expression of TIPRL, Bcl2, and HMG20A to maintain the stemness and survival of CSCs, thus promoting tumorigenesis in lung cancer." (PMID 39076120, 2024). "TIPRL depletion significantly reduced the mRNA and protein levels of Bcl2 and HMG20A, among various potential target genes, in several lung cancer cell lines." (PMID 39076120, 2024). "TIPRL depletion in CD133+ cells isolated from lung cancer cells also decreased the expression of Bcl2 and HMG20A." (PMID 39076120, 2024). "In turn, the activated CREB upregulates the expression of TIPRL, Bcl2, and HMG20A to maintain the stemness and survival of CSCs, thus promoting tumorigenesis in lung cancer." (PMID 39076120, 2024).
infection (3 papers, 2015 to 2024). The state of being infected such as from the introduction of a foreign agent such as serum, vaccine, antigenic substance or organism. "Infections with strain Lp02rpsLWT in Hmg20a-/- BMDMs caused lysosome damage in about 30% cells, which was similar to infections with strain Lp02rpsLK88R on wild-type and Hmg20a-/- BMDMs." (PMID 38739652, 2024). "In line with the decreased cell death rates, infection with strain Lp02rpsLWT caused less cleavage of caspase-3 and PARP in Hmg20a knockout BMDMs than in wild-type cells." (PMID 38739652, 2024). "Depletion of Hmg20a protects macrophages from infection-induced lysosomal damage and apoptosis, allowing productive bacterial replication." (PMID 37961430, 2023). "CP77 associates with HMG20A in the viral factory of infected CHO-K1 cells and is necessary for HMG20A dissociation 8 h post-infection." (PMID 25690795, 2015). "Therefore, it is highly probable that Hmg20a indirectly impacts the cellular processes that regulate the integrity of lysosome membranes in response to Lp02rpsLWT infection." (PMID 38739652, 2024).
cancer (2 papers, 2022). A tumor composed of atypical neoplastic, often pleomorphic cells that invade other tissues. "The HMG20A gene is highly expressed in a variety of cancers, which increases the drug resistance of cancer cells and promotes cell migration." (PMID 36142473, 2022). "The expression of HMG20A in normal tissues and tumor tissues of different cancer stages in TCGA." (PMID 35577773, 2022).
tumor (2 papers, 2022 to 2024). "Meanwhile, rescue experiments with Bcl2‐ and HMG20A‐expressing lentiviral particles were conducted to determine whether the decrease in tumor progression caused by TIPRL depletion was directly linked to the expression of Bcl2 and HMG20A in TIPRL‐depleted cells." (PMID 39076120, 2024). "Knockdown of HMG20A significantly reduced tumor volume and tumor growth, which were further reduced after SFMBT1 knockdown." (PMID 35577773, 2022). "The glandular regions in the CRC tumor tissues are poorly differentiated compared to normal tissues under the higher expression of HMG20A." (PMID 35577773, 2022). "Xenograft experiments were conducted to investigate the role of SFMBT1 and HMG20A in tumor growth and metastasis in vivo." (PMID 35577773, 2022). "Expression of HMG20A was examined in CRC by IHC in tumor tissues and tissue microarrays." (PMID 35577773, 2022). "In TCGA, HMG20A is higher in tumor tissues than in adjacent normal tissues." (PMID 35577773, 2022).
bacterial infection (1 paper, 2022). "Compared to HMGB1, the research on fish HMG20A is limited to Nile tilapia (Oreochromis niloticus), in which it was shown that HMG20A knockdown improved fish survival after bacterial infection." (PMID 36140677, 2022). "Since HMGB1/HMG20A interacted with both PBLs and bacterial pathogens, we investigated whether these proteins could affect the bacterial infection of PBLs." (PMID 36140677, 2022). "In contrast, the treatment with HMG20A had little effect on bacterial infection." (PMID 36140677, 2022).
neurodegenerative disease (1 paper, 2021). A disorder of the central nervous system characterized by gradual and progressive loss of neural tissue and neurologic function. "Failure of those HMG20A-mediated processes leads to astrocyte dysfunction and ineptitude to react resulting in neuron death and to the potential development of neurodegenerative diseases such as AD as well as T2DM, for which a link has previously been established." (PMID 34093866, 2021).
HMG20A also shares sentences with these, for which no sentence is quoted: Alzheimer disease (1 paper); breast carcinoma (1); colorectal cancer (1); epidermoid carcinoma (1); hepatocellular carcinoma (1); Insulin resistance (1); multiple sclerosis (1); myopia (1); Neurodegeneration (1); oral squamous cell carcinomas (1); refractive error (1).